INS (insulin)
Diseases named in the same sentence as INS in open-access papers (continued):
Sharing a sentence is not in itself a finding about the gene and the disease.
Insulin resistance (continued). "Coincidentally, several studies reported that insulin levels increased in the early stage of air pollution, which further proves that long-term air pollution exposure may lead to insulin resistance." (PMID 37999546, 2023). "In support of this, an abundance of evidence demonstrates reduced mitochondrial content in insulin resistant/obese individuals, while genetically increasing mitochondrial content in rodents attenuates lipid-mediated insulin resistance." (PMID 37153211, 2023). "MDED not only positively improves inflammatory biomarkers but also improves clinical parameters such as body weight, waist circumference, liver fat accumulation, blood drug level transaminase, glutamyltransferase, triglycerides, cholesterol, insulin, and insulin resistance." (PMID 37063273, 2023). "Therefore, in this study, increasing adiponectin levels can prevent insulin resistance by increasing insulin sensitivity as well as protecting pancreatic islets from apoptosis due to MetS." (PMID 36985762, 2023). "Triglyceride-induced insulin resistance and impaired insulin secretion in diabetic patients might explain the proposed hypothesis." (PMID 35905014, 2023). "Insulin resistance is a common disorder defined as a state of decreased insulin responsiveness." (PMID 37893085, 2023). "In aged obese rats, insulin sensitivity is increased after melatonin supplementation, suggesting that an age-related decline in melatonin secretion is likely to play a role in the development of insulin resistance in aged organisms." (PMID 37371817, 2023). "Chronic hyperglycemia leads to diminished glucose‐stimulated insulin secretion and increased insulin resistance, and resolving this glucose toxicity is a key to the treatment of T2DM, as the decline in insulin secretion and insulin sensitivity will lead to further hyperglycemia." (PMID 37864379, 2023). "Hence, there is considerable interest in studying adipose insulin action to understand how this tissue contributes to whole-body insulin resistance." (PMID 36808134, 2023). "Here, we show that Ip3r1 deletion in skeletal muscle improved glucose tolerance and insulin sensitivity of mice fed regular diets but accelerated insulin resistance in obese mice, which was confirmed by the decreased insulin-mediated Akt signaling in skeletal muscle." (PMID 36894534, 2023). "Pregnancy-related insulin resistance becomes pathological (as in GDM) when maternal insulin production is unable to increase sufficiently to meet the pregnancy-induced changes in insulin sensitivity, resulting in maternal hyperglycaemia, and consequently increased fetal glucose levels." (PMID 38288471, 2023). "In addition, it was reported in our study that NAC administration improves insulin resistance and insulin secretion compared to placebo." (PMID 37794966, 2023). "Increased plasma leptin levels have often been associated with insulin resistance in human subjects, and a negative correlation between fasting plasma leptin and insulin sensitivity has been reported after adjusting for BMI." (PMID 37964253, 2023). "However, in the context of insulin resistance, the expression of insulin-dependent AMPs is suppressed, creating a less optimal antimicrobial environment, allowing for viable microbes to ascend into the collecting ducts." (PMID 37175805, 2023). "In transgenic rats with the suppressed function of myostatin, insulin signaling was significantly activated and high-fat diet failed to cause glucose intolerance or insulin resistance as compared to wild-type rats." (PMID 37576807, 2023). "We also found that males had significantly higher fed-state plasma insulin concentrations compared to females, which may signify greater insulin resistance in older males than females." (PMID 37836396, 2023). "Finally, SGLT2 inhibitors can reduce plasma glucose and insulin levels and significantly ameliorate insulin resistance and insulin secretion." (PMID 36834946, 2023).
Insulin resistance (continued). "It is arguable whether insulin resistance precedes hyperinsulinemia; insulin resistance is defined as a higher than normative population concentration of insulin to maintain euglycaemia." (PMID 37760052, 2023). "The present meta-analysis aims to assess the impact of insulin action manipulations (i.e., hyperinsulinemia, hypoinsulinemia, systemic or brain insulin resistance) on glutamatergic, dopaminergic, γ-aminobutyric acid (GABA)ergic, and serotonergic pathways in the central nervous system." (PMID 37085712, 2023). "With PA-induced insulin resistance in cells, insulin treatment no longer caused RAS activation, while KRA-533 maintained its effect in promoting RAS activation." (PMID 37884540, 2023). "It is a chronic metabolic disorder in which patients may have problems with insufficient insulin secretion, insulin resistance, or both." (PMID 36983587, 2023). "Moreover, inflammation, which is frequently linked to obesity, exacerbates insulin signaling impairment by inducing serine phosphorylation of IRS-1, resulting in the development of insulin resistance." (PMID 38283440, 2023). "Given inadequate levels of insulin and increased insulin resistance, results in hyperglycemia." (PMID 37072431, 2023). "This suggests that REG3A may enhance insulin action through an Akt-independent mechanism and thus contribute to curb the development of insulin resistance." (PMID 36918710, 2023). "Similarly, berberine increased insulin sensitivity in obese experimental animals, reduced fasting insulin levels by 46%, and reduced the homeostatic model assessment of insulin resistance index (HOMA-IR) by 48%." (PMID 36770960, 2023). "Some of these are related to insulin resistance and insulin secretion." (PMID 37790638, 2023). "Thus, insulin tolerance tests will be conducted in the future to complete insulin resistance results." (PMID 37125029, 2023). "HOMA-IR measures glucose–insulin homeostasis as a method to evaluate insulin resistance." (PMID 36674447, 2023). "With a late diagnosis, insulin production-related genes from chromosome region 11p15.5 notably influenced males while peripheral insulin resistance and genes associated with inflammation and other processes notably influenced females." (PMID 37291636, 2023). "Optimal levels of selenium may enhance insulin sensitivity and glucose regulation, but excessive selenium could promote insulin resistance, leading to the development of T2D." (PMID 37630213, 2023). "Finally, activation of SIRT1 leads to insulin-stimulated translocation of GLUT4 storage vesicles (GSVs) from intracellular storage pools to the plasma membrane resulting in improvement of insulin resistance." (PMID 38027557, 2023). "Furthermore, chronic stress can lead to insulin hypersecretion, leading to insulin resistance and potentially contributing to the accumulation of (visceral) fat in the long term." (PMID 37746434, 2023). "Inflammatory cytokines impair insulin signalling and trigger insulin resistance." (PMID 38066566, 2023). "However, usually around the beginning of the second trimester, insulin resistance rises while insulin secretion remains unchanged, leading to maternal hyperglycemia." (PMID 37239090, 2023). "Indices of insulin sensitivity /Insulin resistance were computed based on established formulae." (PMID 37928491, 2023). "In Drosophila, cytokines can induce insulin resistance, and insulin resistance could occur despite the increase in InR transcription in muscle." (PMID 37334669, 2023). "SHBG is regulated by insulin, and insulin resistance decreases its synthesis and secretion." (PMID 38317710, 2023). "Baseline levels of glucose, insulin, homeostasis model assessment of insulin resistance (HOMA-IR), TG, and fasting serum total P, K, and Mg were within normal ranges and were found to be similar between the different experimental sessions for each type of bread." (PMID 37892534, 2023).
Insulin resistance (continued). "Previous studies show that hypertrophy or an increased number of adipose cells results in the enhanced or weakened expression of its secreted hormones and adipokines, which affects the effects of insulin from different levels, and further induces or exacerbates the presence of insulin resistance." (PMID 36983677, 2023). "They act by decreasing insulin resistance and enhancing insulin sensitivity." (PMID 37049636, 2023). "Finally, to confirm the involvement of PTP1B in the mechanism of HFD- and HCI-induced insulin resistance, we evaluated insulin signaling in plantaris muscle treated with a PTP1B inhibitor after HFD and HCI." (PMID 37389126, 2023). "Therefore, the results of previous studies in which higher levels of leptin are related to higher levels of insulin and, consequently, insulin resistance due to a break in the insulin signaling pathway caused by hyperinsulinemia are supported." (PMID 37299591, 2023). "Additionally, eating fewer than two meals per day has been associated with higher calorie consumption per meal, resulting in a rapid increase in postprandial glucose levels, which induces an enhanced insulin response and eventually leads to insulin resistance." (PMID 37165359, 2023). "Blood glucose levels measured 30 min after insulin injection were higher in the diabetic and drug-administered groups than in the normal group; however, insulin resistance in the drug-administered groups tended to improve compared to that in the diabetic group." (PMID 37754257, 2023). "Type 2 diabetes (T2D) is a chronic disease that causes a patient’s body not to respond normally to insulin called insulin resistance." (PMID 35946077, 2023). "PDC has the overall characteristics of metabolic disorders, with pathological characteristics such as abnormal distribution of body fat, lipid metabolism disorders, high levels of insulin, and insulin resistance, and is related to a variety of metabolic-related diseases." (PMID 37101714, 2023). "More importantly, we found that chronic increase in beta cell workload (increased insulin demand and insulin resistance) induces ER stress and impairment of the beta cell secretory machinery, as shown in the altered expression of in situ proinsulin/insulin ratio." (PMID 36280617, 2023). "Therefore, in a previous study where insulin resistance increased insulin secretion increased correspondingly which is expected in studies having short follow-up." (PMID 37795366, 2023). "CB2 receptors may also regulate insulin secretion, insulin resistance, obesity-related inflammation, and metabolic changes such as nonalcoholic fatty liver disease." (PMID 36949158, 2023). "L. plantarum and inulin can exert antidiabetic and antioxidant properties via improving insulin resistance and hyperlipidemia as well as hypothalamic levels of insulin, leptin, and oxidative markers in T2DM rats, and their combined recovery effect is superior to that of their use alone." (PMID 37734909, 2023). "Indeed, mice treated with STZ and HFD, which show insulin resistance and decompensation of insulin-secretion have been widely used as a model of type 2 diabetes." (PMID 37852976, 2023). "In a similar way, the OLE supplementation of the CAF-R diet also corrected metabolic markers such as serum glucose and insulin sensitivity, in addition to triacylglycerides, insulin, and insulin resistance levels whereas the CAF-R diet alone only normalized the insulinaemia." (PMID 36837766, 2023). "Unfortunately, this therapy is not clinically effective—rapamycin improves insulin sensitivity initially but long‐term causes hyperglycemia and insulin resistance." (PMID 38114067, 2023). "SULFs and glinides are insulin secretagogues, while TZDs are the only OADs specifically treating insulin resistance by activating the peroxisome proliferator-activated receptor γ (PPAR-γ), but their use in clinical practice is limited due to skepticism about safety and tolerability." (PMID 36902770, 2023).
Insulin resistance (continued). "The presented results of the study on carbohydrate metabolism disorders may further indicate the need for the application of different, higher norms for both insulin concentrations and insulin resistance indices during the adolescent period." (PMID 37892696, 2023). "It is reported that TNF-α has been linked to signaling pathway of insulin impairment by increasing serine phosphorylation of IRS-1, which inhibits activity of tyrosine kinase resulting in impaired downstream signaling and development of insulin resistance." (PMID 37089941, 2023). "Secondary outcomes were changes in insulin AUC, insulin resistance assessed using the Homeostatic Model Assessment for Insulin Resistance (HOMA-IR), β-cell function (HOMA-β), Matsuda Insulin Sensitivity Index, cardiometabolic risk markers and autophagy gene expression." (PMID 38004206, 2023). "In conclusion, although various PCs have different mechanisms of action in DM, what these effects have in common is improving insulin resistance and increasing insulin sensitivity, and anti-inflammatory and anti-oxidative stress are at the core of these effects." (PMID 37009462, 2023). "Feeding experimental rats with an HFHS diet for 8 weeks has resulted in a significant increase (p < 0.001) in body weight, HbA1C%, the levels of lipid profile markers, fasting serum glucose, and insulin as well as insulin resistance represented by HOMA-IR, compared to the Sham animals." (PMID 36915161, 2023). "Similarly, insulin signaling defects can also be detected in tissues of patients with other types of insulin resistance." (PMID 37972259, 2023). "Indeed, insulin AUC strongly and positively correlates with indexes of insulin resistance, e.g., HOMA-IR." (PMID 37108445, 2023). "A key result of our research was that we detected cut-off values for leptin and insulin, which may potentially be additional predictors of insulin resistance and obesity." (PMID 37373485, 2023). "To confirm the interaction between dysregulated mitochondrial energy expenditure and mitochondrial translation in relation to insulin resistance in humans, we utilized gene expression data from insulin-resistant and insulin-sensitive obese subjects obtained from the GEO database." (PMID 37836502, 2023). "Young people with obesity have hyperinsulinemia and suffer peripheral resistance to the action of insulin (insulin resistance, IR) with an approximately 40% reduction in peripheral insulin sensitivity, meaning reduced glucose uptake in the muscle tissue and increased lipolysis in the adipose tissue." (PMID 36980074, 2023). "We additionally found differential relationships of NT‐proANP with measures of insulin concentration and insulin sensitivity/resistance among AA and EA participants, suggesting that higher fasting insulin, secondary to insulin resistance, contributes to lower ANP in EA individuals." (PMID 36905117, 2023). "Given that the network of insulin/IGF-1 receptor signaling pathway is essential in brain, upregulation of blood adiponectin may reflect a compensatory feedback response to abnormally reduced insulin/IGF-1 receptor signaling due to insulin resistance." (PMID 37191420, 2023). "Changes in the insulin signalling pathway may therefore underpin the association between PCOS and EC as insulin resistance is a key feature of PCOS, though the precise molecular mechanisms which underpin this association remains unclear." (PMID 37737665, 2023). "Notably, oxidative stress, TNF-α, and IL-1β activate the c-Jun NH2-terminal kinase (JNK), generating insulin signaling interruption by modifying the phosphorylation of insulin receptor and insulin receptor substrate-1, provoking insulin resistance." (PMID 36976988, 2023). "Interestingly, insulin resistance also developed only in males, with estrogen having been found to additionally confer insulin sensitivity." (PMID 37789041, 2023).
Insulin resistance (continued). "Because of insulin resistance and insufficient secretion of insulin from pancreatic β cells, increased glucose production in the liver along with reduced glucose utilization in insulin-sensitive tissues, such as muscle and adipose tissues, lead to hyperglycemia in these patients." (PMID 36836874, 2023). "Furthermore, the phosphorylation of IRS‐1 at Ser307 attenuates insulin signaling and contributes to insulin resistance." (PMID 38107110, 2023). "LPS receptor CD14 knockout mice fed a high-fat diet or injected with LPS had decreased inflammatory factors in adipose tissue, increased insulin sensitivity in liver and adipose tissue, and had a delayed development of insulin resistance, and their weight gain slowed down." (PMID 36902554, 2023). "And in newly diagnosed patients with type 1 diabetes (caused by inadequate insulin production but not insulin resistance), morphological changes of DKD were absent, but appear after insulin resistance develops." (PMID 37153213, 2023). "In another report of middle-aged Caucasian participants who were generally healthy, poor sleep quality was significantly related to metabolic syndrome, and a significant association was found between sleep quality and fasting glucose, insulin, and insulin resistance." (PMID 37109236, 2023). "As a result, development of hepatic steatosis after pancreatectomy may have several driving factors including insulin resistance, decreased insulin production, malnutrition, and EPI." (PMID 36705353, 2023). "Berberine is reported to act by several mechanisms, including increasing insulin secretion, improving insulin resistance, inhibiting gluconeogenesis, increasing glucose uptake, inducing glycolysis, inhibiting the action of several important enzymes, and regulating the gut microbiota." (PMID 36770960, 2023). "Additionally, the PJE group showed lower levels of serum insulin, insulin resistance, and glucose compared to the DIO control group." (PMID 37107470, 2023). "Such damage could precipitate a decline in insulin secretion and foster insulin resistance, both of which are crucial characteristics of T2D." (PMID 37998725, 2023). "It has been shown that a diet rich in n-3 PUFAs improves insulin sensitivity and may prevent the development of insulin resistance in response to high-fat feeding and modulates the expression and secretion of adipocytokines." (PMID 38068822, 2023). "Laboratory studies suggest that specific alkaloids can intervene in the insulin signal transduction pathway, and reverse molecular defects that could otherwise lead to insulin resistance and glucose intolerance." (PMID 36980642, 2023). "Vice versa, leptin can influence insulin and insulin resistance." (PMID 38068822, 2023). "However, if regular levels of insulin fail to achieve the desired response from insulin receptors, insulin resistance can develop." (PMID 38021940, 2023). "This indicates that insults causing insulin resistance do not just attenuate insulin signaling, rather they rewire the insulin-responsive signaling network." (PMID 36808134, 2023). "Insulin resistance and weight loss in the CIC mouse model were partially improved by treatment with an insulin-sensitizing agent, rosiglitazone, suggesting that targeting insulin resistance could be a useful way to deal with CIC." (PMID 36831310, 2023). "Maternal obesity was associated with hyperinsulinemia and insulin resistance in the offspring, indicated by higher serum insulin levels and HOMA-IR scores, when compared to the offspring of lean mothers (serum insulin: C vs. H, p < 0.01, HOMA-IR: C vs. H, p < 0.001)." (PMID 38201940, 2023). "Patients with ME/CFS may present with insulin resistance, increased blood insulin levels, high waist circumference, high triglycerides, and hypocortisolism." (PMID 37718435, 2023). "As expected, HFD increases fasting insulin and c-peptide levels, indicative of insulin resistance." (PMID 37142604, 2023).